MC1R (melanocortin 1 receptor)
Diseases named in the same sentence as MC1R in open-access papers (continued):
Sharing a sentence is not in itself a finding about the gene and the disease.
melanoma (continued). "We are conducting a randomized controlled trial examining Internet presentation of the risks and benefits of personalized genomic testing for MC1R gene variants that are associated with increased melanoma risk." (PMID 28442450, 2017). "The comparative analysis of melanoma patients with WT and null MC1R alleles have a significantly higher mutational load than individuals with no R alleles." (PMID 29156643, 2017). "Other studies have reported statistically significant, but small to modest improvement in prediction of melanoma risk by adding MC1R genotype to traditional demographic and pigmentation characteristics." (PMID 28323902, 2017). "Variants of the melanocortin-1 receptor gene (MC1R) confer moderate melanoma and basal cell cancer risks in the general population." (PMID 28442450, 2017). "As MC1R has already beensuggested to affect melanogenesis and increase risk of developing melanoma, itconstitutes one of the best models to understand how natural selection acts onpigmentation." (PMID 28486572, 2017). "There has been little research in Chinese Han populations on clinico-dermoscopic variability of naevi or how naevi are affected by melanoma-linked variants of the melanocortin 1 receptor (MC1R) gene." (PMID 29340229, 2017). "The results also included 10 SNPs previously identified for melanoma risk reported at MC1R (2 SNPs), MX2, TERT/CLPTM1L, PLA2G6, CASP8, ACTRT3, ASIP, CDC91L1, and ARNT/SETDB1/LASS2ANXA9/MCL1/CTSK." (PMID 27993549, 2017). "It was reported that the improvement of melanoma risk prediction by adding MC1R to age, sex, and cutaneous melanin phenotypes is modest and too small to be valuable in clinical setting." (PMID 28323902, 2017). "Polymorphism in MC1R is linked to increased melanocyte apoptosis and inefficient DNA repair, and is related to increased melanoma risk." (PMID 29156643, 2017). "As melanoma cells overexpress membrane-bound melanocortin type 1 receptors (MC1Rs), suitable ligands for MC1R are candidates for targeting melanoma with diagnostic or therapeutic radioisotopes or toxin conjugates." (PMID 28491052, 2017). "Genetically, pig melanoma is a complex trait with incomplete penetrance, and although high-risk genes remain to be discovered, MC1R has been involved beyond pigmentary phenotypes." (PMID 29081790, 2017). "The melanocortin 1 receptor gene,MC1R, is associated with fair skin, red hair, and increased risk for melanoma and NMSC25–30." (PMID 29259776, 2017). "A microsatellite located close to MC1R was linked to melanoma, even when the analysis was corrected for coat color, proving that pigmentation variation was not the only effect." (PMID 29081790, 2017). "Deleterious germline variants in the MC1R gene are associated with red hair and freckles, and with an increased risk of developing melanoma." (PMID 27403562, 2016). "Many polymorphic variants were associated with melanoma, including those located in melanocortin 1 receptor gene (MC1R), which encodes a receptor protein involved in melanogenesis." (PMID 27058533, 2016). "Despite this limitation, developing these analogs as a skin cancer, including melanoma, prevention strategy will benefit millions who are heterozygous for MC1R variants, and have a high risk for melanoma due to reduced MC1R activity." (PMID 27582758, 2016). "With the exception of mutations in MC1R, few studies have addressed the genetics of predisposition to melanoma development in animal models." (PMID 26354726, 2016). "In summary, we find a role for germline MC1R variants in influencing the somatic mutational landscape of melanoma." (PMID 27403562, 2016). "The human MC1R is highly polymorphic, and MC1R variants, particularly those that cause loss of function of the expressed receptor, are associated with increased melanoma risk independently of pigmentation." (PMID 27582758, 2016). "The association of this pigmentary phenotype with increased melanoma risk implicated the MC1R in melanoma predisposition." (PMID 27582758, 2016).
melanoma (continued). "The vast interest in MC1R stems from its high polymorphism and its role as a melanoma susceptibility gene." (PMID 27582758, 2016). "In this study, we set out to establish the contribution of germline MC1R alleles to the somatic mutation landscape of sporadic melanoma." (PMID 27403562, 2016). "These epidemiological results concluded that melanoma risk cannot be accurately ascertained based only on pigmentary phenotype, and suggested that MC1R regulates other functions in melanocytes, independently of pigmentation." (PMID 27582758, 2016). "MC1R mutations are also associated with a reduced DNA-repair capacity, possibly explaining the link between MC1R and melanoma risk." (PMID 26482799, 2015). "We performed genetic analysis of CDKN2A, CDK4, BAP1, MC1R, and MITFp.E318K in Danish high-risk melanoma cases and found CDKN2A germline mutations in 11.3% of CM families with three or more affected individuals, including four previously undescribed mutations." (PMID 25803691, 2015). "Epidemiological studies have shown loss-of-function MC1R variants are associated with higher risk of developing melanoma." (PMID 26504519, 2015). "Minor allele frequency (MAF) and odds ratio (OR) of MC1R variants in melanoma cases/families compared to the Danish population." (PMID 25803691, 2015). "Inherited variation in the melanocortin-1 receptor (MC1R) gene is a robust genetic marker for moderately increased risk of melanoma." (PMID 25790105, 2015). "Variation in the melanocortin-1receptor (MC1R) gene is associated with pigmentary phenotypes and risk of malignant melanoma." (PMID 25790105, 2015). "1Contrary to the evidence, Aunt’s 23andMe report predicts a decreased risk for Melanoma based on two SNPs (rs1805007 and rs1805008) located in MC1R." (PMID 26547235, 2015). "The age-specific penetrance for CM in CDKN2A mutation carriers is high in Denmark, as in other high incidence melanoma countries, and MC1R variants modulate the penetrance of CM and the risk of MPM." (PMID 25803691, 2015). "Despite its small size (951 bp), the MC1R gene harbors a high number of polymorphisms, including several loss-of-function mutations that are associated with reduced skin color, melanoma, freckling, and red or blond hair." (PMID 26482799, 2015). "Recently, Peña-Vilabelda et. al. reported results similar to our own with respect to high-risk MC1R variants in association with melanoma tumor site presentation (Arms: OR = 2.34; 95% CI: 0.98, 5.61)." (PMID 25790105, 2015). "CDKN2A mutation carriers with [R/R, R/r] MC1R genotypes, had a significantly higher risk of developing melanoma compared to other carriers, and had an OR of 2.25 for developing CM 10 years earlier than carriers with [r/r, R/wt, r/wt, wt/wt] MC1R genotypes." (PMID 25803691, 2015). "PTEN (or rather lack of PTEN) was shown to play a key role in the predisposition to melanoma in individuals carrying certain variants of melanocortin-1 receptor (MC1R)." (PMID 24743024, 2014). "MC1R is also involved in UV-induced DNA repair; and several of its 80 known variants are associated with melanoma risk." (PMID 25003831, 2014). "Among pigmentation genes, MC1R, which is the most studied, is associated with human skin pigmentation and melanoma susceptibility." (PMID 24982914, 2014). "The influence of MC1R r variants on melanoma risk has also been reported but there are several discrepancies in the different published works." (PMID 24982914, 2014). "In conclusion, we demonstrated that the inclusion of indoor tanning measures and MC1R genotype improve the predictive ability of a clinically-based melanoma risk model." (PMID 25003831, 2014). "In this large study we confirmed the role of MC1R R alleles in melanoma susceptibility and clearly showed that MC1R r alleles also significantly increase the risk of melanoma." (PMID 24982914, 2014). "We also showed a clear association of frequent MC1R r alleles, especially V60L, V92M, and I155T, with melanoma." (PMID 24982914, 2014).
melanoma (continued). "The pigmentation related gene MC1R acts as a moderate melanoma risk gene and variants in this gene are modifying factors for melanoma risk in CDKN2A mutation carriers." (PMID 24742402, 2014). "Numerous association studies have demonstrated the important role of MC1R R variants in melanoma predisposition." (PMID 24982914, 2014). "Among genetic factors associated with melanoma, polymorphisms in the melanocortin-1 receptor (MC1R) are common and exhibit moderate penetrance." (PMID 25003831, 2014). "Studies have separately demonstrated significant associations between melanoma risk, melanocortin receptor (MC1R) polymorphisms, and indoor ultraviolet light (UV) exposure." (PMID 25003831, 2014). "In conclusion, we have identified baseline expression signatures in skin cells carrying germline CDKN2A mutations and RHC MC1R variants which are maintained in skin tumors (melanoma and squamous cell carcinomas)." (PMID 24742402, 2014). "In this large French case-control study, we investigated the role of different classes of MC1R variants in melanoma risk, focussing particularly on the role of rare MC1R variants." (PMID 24982914, 2014). "In order to study the impact of MC1R protein domains on melanoma predisposition, the different classes of MC1R variants (R, r, D, and nD) were positioned on the different protein domains." (PMID 24982914, 2014). "This contrasting effect in melanoma susceptibility derived from the direct effect of natural selection has recently been observed also in the evolution of the pigmentary gene MC1R in Europeans." (PMID 25093503, 2014). "We have recently shown the presence of signatures of positive selection acting over the pigmentation and melanoma-risk locus MC1R in Europeans." (PMID 25093503, 2014). "Although MC1R genotype is strongly associated with skin and hair phenotype, it was a better predictor of early-onset melanoma than was pigmentation characteristics." (PMID 24134749, 2013). "Our study results will help guide the development of melanoma risk prediction tools that incorporate MC1R genotype." (PMID 24134749, 2013). "In meta-analyses, rs1805007 showed the highest attributable risk for melanoma among MC1R variants with effect estimates similar to those found in this study and a previous Greek case-control study." (PMID 23393597, 2013). "The “red hair” variant rs1805007 of the MC1R gene has been consistently linked to melanoma risk in relevant studies." (PMID 23393597, 2013). "Three other, preliminary, melanoma risk prediction models containing MC1R genotype have been published." (PMID 24134749, 2013). "MC1R variants have been associated with a 1.2 to 2.4-fold increased risk of melanoma with an additive effect for multiple variants." (PMID 22978401, 2012). "Allelic variants in the MC1R gene, important in the pigmentation process, have been associated with increased melanoma risk, with the strongest effect observed for red hair color (RHC) variants (p.ArgR151Cys, p.Arg160Trp, p.Asp294His)." (PMID 22978401, 2012). "Identification of two high-risk MC1R variants in our identical twins in the absence of CDKN2A and CDK4 mutations highlights the contribution of low penetrance genes, such as MC1R, in melanoma susceptibility." (PMID 22978401, 2012). "Two high-penetrance susceptibility genes, CDKN2A and CDK4 and one low-penetrance gene, MC1R, are well-defined genetic risk factors for melanoma." (PMID 22978401, 2012). "With this in mind, the emergence of MITF's role in melanoma and its high frequency of duplication, it seems contradictory that MC1R mutants predispose individuals to this disease." (PMID 22316093, 2012). "There was support for a protective effect of variant ‘R’ or ‘r’MC1R on death from melanoma from the other nine cohorts, although overall the result from those nine cohorts was not independently statistically significant." (PMID 22325793, 2012).
melanoma (continued). "This study reports a survival analysis of a large cohort of melanoma patients from the UK, which identified an effect of hair color and inherited variants in the MC1R gene on OS." (PMID 22325793, 2012). "The role of SLC45A2 in melanoma predisposition was further analyzed in relation to MC1R, the main low penetrance gene associated to melanoma." (PMID 21559390, 2011). "Other genes, such as MC1R (Melanocortin 1 Receptor) and DNA repair genes, are likely to be more important in determining susceptibility for melanoma in the general population." (PMID 20936153, 2010). "Additional genetic risk factors for melanoma appeared to be polymorphisms in genes controlling skin color, positioned in the melanocortin-1 receptor pathway." (PMID 24281082, 2010). "Melanoma risk is associated in the individuals with the pale skin pigment and individuals with selected MC1R gene variants have an increased risk for melanoma development that is independent of skin type and hair color." (PMID 22545195, 2010). "This clinical observation has been supported by a study in Sweden where MC1R variants (red hair, light skin) were found to be associated with an increased risk of melanoma in members of hereditary melanoma families." (PMID 24281082, 2010). "The fact that variants in the MC1R receptor gene control, at least in part, some of melanoma risk factors such as red hair and freckles, identify MC1R as a candidate probably low risk melanoma susceptibility gene." (PMID 24281082, 2010). "Considering the individuals who were either homozygous or heterozygous for the "R" variant of the MC1R gene, the occurrence of such a "R" allele into the genotype was significantly associated with melanoma (p = 0.043; OR, 2.3; 95% CI, 1.2-7.8)." (PMID 19799798, 2009). "Two MC1R germline variants, Arg151Cys and Asp294His, were significantly associated with melanoma in Sardinia." (PMID 19799798, 2009). "Several low-penetrance candidate genes, such as breast cancer susceptibilitygene 2 (BRCA2) and melanocortin-1-receptor (MC1R), have been also implicated in melanoma predisposition." (PMID 19799798, 2009). "MC1R variants are also associated with increased risk of malignant melanoma in a variety of populations, MC1R gene product has been proposed as a new marker and a putative therapeutic target for uveal melanoma." (PMID 19017395, 2008). "MC1R variants have been associated with melanoma risk among individuals of European descent and as a modifier of melanoma risk in CDKN2A mutation-positive CMM families." (PMID 18803848, 2008). "The link between tanning and risk for melanoma lies in polymorphisms in the MC1R (melanocortin receptor 1) gene, which impair the tanning response to UV light." (PMID 18813259, 2008). "Among these, loss of function variants of the human melanocortin-1 receptor gene, which plays a crucial role in pigmentation, seems to have an important role in determining melanoma risk." (PMID 14735200, 2004). "This suggests that certain MC1R variants can exert an effect on melanoma tumorigenesis in a dual manner, both as a determinant of fair skin and as a component in an independent additional pathway." (PMID 14612910, 2003). "The present report contains several new observations relevant to the potential use of MC1R in diagnostic and immunotherapy of melanomas." (PMID 12177778, 2002). "However, the progeny generated by crossing MC1R loss-of function mice with re-expressed MC1R variants to BRAF mutant mice were characterized by the early development of melanomas following weekly UVR treatment (up to 4 weeks)." (PMID 40004137, 2025). "Patients with advanced melanoma undergoing ICI treatment were genotyped for MC1R variants." (PMID 40926353, 2025). "In this context, a BioGenoMel collaborative study aimed at verifying the hypothesis that inherited MC1R variants may impact melanoma survival expectation." (PMID 40869905, 2025). "Mutations in the MC1R gene are among the most well-established genetic risk factors for melanoma." (PMID 40507265, 2025).
melanoma (continued). "For instance, variants of the MC1R gene, which are prevalent among light phototypes, are linked to poorly pigmented melanomas that are challenging to identify due to their poor pigmentary structures and atypical vascular patterns when examined using dermoscopy." (PMID 40558591, 2025). "Additionally, MITF (p.E318K variant) and pigmentation-related genes like MC1R influence melanoma susceptibility, particularly through UV sensitivity." (PMID 39941357, 2025). "Furthermore, some downregulated genes following MC1R knockout have been implicated in cell migration and melanoma metastasis, but its role in CRC cell migration and metastasis remains uncharacterized and warrants further investigation." (PMID 40547309, 2025). "Identifying the prevalence of various MC1R variants in LM/LMM within the Utah population may yield additional insights into the pathogenesis of melanoma subtype development and may inform strategies for skin cancer screening in higher-risk patient populations." (PMID 40673485, 2025). "Patient-specific factors like skin type, red hair, and genetic variations (e.g., MC1R polymorphisms) could partially explain observed differences in melanoma incidence." (PMID 38539502, 2024). "Consequently, a higher somatic mutation burden has been demonstrated in melanoma from subjects with MC1R variants compared to individuals with the wild-type sequence." (PMID 38473275, 2024). "Interestingly, when considering phenotypic characteristics, it was shown that MC1R–associated melanoma risk increased only for darker-pigmented Caucasians, subjects with no freckles, no red hair and skin type III or IV." (PMID 38473375, 2024). "MC1R is critical in melanoma, with its variants increasing UV sensitivity and cancer risk." (PMID 39598465, 2024). "Common variants of the MC1R gene play a relevant role also in sporadic melanoma onset." (PMID 38473275, 2024). "However, it should be noted that polymorphisms of MC1R are associated with increased melanoma risk not only due to decreased pigment shielding but also due to additional factors, e.g., decreased DNA repair." (PMID 38892387, 2024). "Moreover, genetic variations in the Cyclin-dependent kinase inhibitor 2A (CDKN2A) gene, and melanocortin 1 receptor (MC1R) genetic polymorphisms are associated with an increased risk of developing melanoma." (PMID 39339235, 2024). "Some of the specific MC1R variants linked to melanoma risk include R151C, R160W, D294H, and D84E." (PMID 37504268, 2023). "Protection against oxidative lesions by MC1R agonists has been reported for WT MC1R, where it was most likely dependent on cAMP signaling; however, a recent report showed its occurrence in melanoma cells of variant MC1R genotype, where it relied most likely on cAMP-independent signaling." (PMID 37762683, 2023). "Red hair and MC1R loss-of-function variants have also been reported to be associated with increased risk for Parkinson’s disease (PD), a common neurodegenerative disease that has been consistently linked to melanoma." (PMID 38110615, 2023). "Indeed, a meta-analysis of MC1R carriers for these variants reported odds ratio values consistent with their high-risk association with developing melanoma." (PMID 37762683, 2023). "MC1R, a G-protein coupled receptor, triggers ultraviolet light-induced melanin synthesis and DNA repair in melanocytes and is implicated in the pathogenesis of melanoma." (PMID 37679505, 2023). "It is also possible that in some of these families, the increased risk for melanoma may be related to the MC1R genotype combined with environmental exposure since melanin synthesis is related to melanoma progression." (PMID 37958811, 2023). "Thus, although its penetrance is low-to-moderate, the contribution of MC1R variants to melanoma burden is important, as it confers a 60% higher risk to carriers." (PMID 37762683, 2023).